MTOR (mechanistic target of rapamycin kinase)
Diseases named in the same sentence as MTOR in open-access papers (continued):
Sharing a sentence is not in itself a finding about the gene and the disease.
lung cancer (continued). "HC may inhibit PI3K/Akt/mTOR and ERK1/2 signaling pathways in human lung cancer cells, while IL17A can inhibit PI3K/Akt/mTOR-mediated autophagy, which causes lung inflammation and fibrosis." (PMID 35891565, 2022). "Hence, the expression levels of key proteins, i.e., Akt and p-Akt, mTOR and p-mTOR, PI3K and p-PI3K and cell proliferation marker, c-Myc were monitored in the A549 lung cancer cells treated with various concentrations of 24MD (0–100 μM) for 24 h." (PMID 36234769, 2022). "Because mTOR inhibitors in combination with CDK4/6 inhibitors was reported, we thus investigated the effect of the combination of abemaciclib and gilteritinib in lung cancer cells." (PMID 35814226, 2022). "Moreover, fucoidan from Fucus vesiculosus inhibits lung cancer cell migration and invasion via phosphatidylinositol-3-kinase (PI3K)/Akt and the mammalian target of rapamycin (mTOR) signaling." (PMID 35630678, 2022). "In other studies of KRASmut lung cancer, anti-PD-1 combined with inhibition of the AKT-mTOR pathway by mTOR inhibitor or the STAT3 pathway by natural compound luteolin can remarkably decreased the expression of PD-1 or PD-L1, respectively, which consequently surmounts the resistance to anti-PD-1." (PMID 35582540, 2022). "Interestingly, we found that lung cancer cohorts with genetic alterations of EGFR, MAP2K1, mTOR, TEAD1, and YAP1 exhibited worse prognoses of overall, disease-specific, and progression-free survival compared to patients with wild-type (WT) genes." (PMID 35655775, 2022). "Furthermore, MET significantly inhibited breast and lung cancer cell proliferation when combined with Paclitaxel by inducing AMPK activation and inhibiting mTOR levels." (PMID 35186762, 2022). "Several PI3K/AKT/mTOR-targeted therapies, such as buparlisib (PI3K inhibitor), MK2206 (AKT inhibitor), sirolimus (mTOR inhibitor), and perifosine (dual PI3K/AKT inhibitor), are undergoing clinical trials as treatments for lung cancer." (PMID 34279440, 2021). "Scutellarin (SCU) enhanced inhibition of 125I‐induced proliferation, promoted 125I‐induced apoptosis, and boosted 125I‐induced tumor inhibition in vivo in non‐small cell lung cancer (NSCLC) cells, as well as enhanced downregulation of the 125I‐induced AKT/mTOR pathway." (PMID 34255431, 2021). "In all, our data suggest that FBLN2 may suppress lung cancer cell proliferation through regulating MAPK/ERK and PI3K/AKT/mTOR pathways." (PMID 34769264, 2021). "PKD1 also regulates cell proliferation and cell migration through mammalian target of rapamycin (mTOR) and Janus kinase (JAK) signals, but in the lung cancer cell line (A549), PKD1 inhibits cell migration and functions as a tumor-suppressor protein in some cases." (PMID 34064452, 2021). "Interestingly, the ALK inhibitor Ceritinib decreased mTOR activity and increased GFP-WIPI1 dot formation in H3122 and H2228 EML4-ALK+ lung cancer cells, suggesting autophagy activation." (PMID 33907223, 2021). "As other researchers have found that SLC15A4 may have a great impact on the mTOR pathway, the functions of SLC15A4 in the proliferation of lung cancer cells should also be revealed." (PMID 34168674, 2021). "LncRNAs regulate the sensitivity of lung cancer cells to EGFR‐TKIs chiefly through one of the following mechanisms: 1) MAPK/ERK signaling pathway, 2) PI3K/AKT/mTOR signaling pathway, 3) STAT3 signaling pathway, 4) mitochondrial pathway, 5) cell cycle progression, or 6) EMT." (PMID 33931980, 2021). "Together with the mTOR inactivation and activation of PTEN this leads to inhibition of the PI3K/AKT/mTOR signaling pathway resulting in down-regulation of proliferation and migration of lung cancer cells, cell cycle arrest, and non-apoptotic cell death." (PMID 34595181, 2021).
lung cancer (continued). "This study investigated the effects of SCU and 125I on the proliferation and apoptosis of human lung cancer A549 and H1975 cells, and whether SCU and 125I affect the biological behavior of NSCLC through the AKT/mTOR pathway." (PMID 34255431, 2021). "Interestingly, UA induces mitophagy via the Akt-mTOR signaling pathway and is dependent on PINK1 in A549 human lung cancer cells." (PMID 34512368, 2021). "The results showed that high-fat diet (HFD)-related obesity could promote the development of urethane-induced lung cancer in C57BL/6J mice, and the leptin-mediated activation of PI3K/Akt/mTOR/STAT3 pathway was involved in the mechanism." (PMID 33708630, 2021). "Interestingly, studies had reported that miR-99a is induced to be down-regulated when c-Src is activated, and re-overexpressed miR-99a can target mTOR/FGFR3 to inhibit Src-related oncogenic pathways and thereby inhibit the growth of lung cancer cells." (PMID 34307154, 2021). "Furthermore, the importance of phosphoinositide 3-kinase (PI3K)/protein kinase B (AKT)/mammalian target of rapamycin (mTOR) signaling for maintaining the CSC phenotype in renal cell cancer, prostate cancer, and lung cancer has been confirmed." (PMID 33014829, 2020). "First, to clarify whether a combination of anticancer drugs with different mechanisms could induce higher cell death of lung cancer cells, we used a DNA damaging agent (cisplatin (CDDP), HDAC inhibitor (LBH589) and mTOR inhibitor (rapamycin)." (PMID 31856355, 2020). "We hypothesize that the suppressive activity of RPE against lung cancer cell proliferation and early metastasis occurs via the EGFR-MAPK and mTOR-Akt signaling pathways." (PMID 33158043, 2020). "Hence, a study in NSCLC cell lines harboring EGFR wild type has shown that gefitinib promotes autophagy and apoptosis, leading to lung cancer cell death, via blockade of the PI3K/AKT/mTOR pathway." (PMID 32190291, 2020). "Moreover, we find that FAM83A promotes lung cancer progression through ERK and PI3K/Akt/mTOR pathways, suggesting this protein has potential as a therapeutic target for NSCLC." (PMID 32218702, 2020). "Previous studies in colon cancers, rhabdomyosarcomas, lung cancers, glioblastomas, and ovarian cancers demonstrated that under conditions of cellular duress, including treatment with ABT-263, Mcl-1 protein levels are induced downstream of mTOR signaling." (PMID 31595181, 2019). "Down‐regulation or inhibition of PRMT5 markedly reduced Akt phosphorylation at Thr308 and Ser473, whereas the expression of PTEN and mTOR phosphorylation was unchanged, indicating that PRMT5 was an important upstream regulator of Akt and induced lung cancer cell proliferation." (PMID 30461193, 2019). "Results showed that the combination of IPA-3 plus auranofin abrogated the expression of total/phosphorylation of PAK1, PKCι, ERK 1/2, mTOR, AKT, and YAP1 in the 3 lung cancer cell lines studied HCC827 (EGFR-mutant LUAD), H23 (KRAS-mutant LUAD) and H520 (PAK1 overexpression)." (PMID 31660987, 2019). "The dual PI3K/mTOR inhibition by BEZ235 is an effective antitumor strategy for enhancing the efficacy of chemotherapy or targeted therapy, even as a monotherapy, to restrict tumor growth in lung cancer treatment." (PMID 31262325, 2019). "Very recently, CT has also been reported to inhibit the proliferation of A549 human lung cancer cells through a signaling pathway involving induction of reactive oxygen species, activation of JNK, downregulation of mTOR, and ultimately formation of pro-death autophagy." (PMID 30972427, 2019). "In this study, IARS2 knockdown promoted mitochondria-dependent apoptosis, suggesting that IARS2 may promote lung cancer cell proliferation and inhibit apoptosis through abnormal activation of AKT/MTOR signaling." (PMID 31157169, 2019). "Collectively, these results demonstrate that PRMT5 directly interact with Akt but no PTEN or mTOR in human lung cancer cells." (PMID 30461193, 2019).
lung cancer (continued). "We further demonstrated that protective autophagy could occur simultaneously in lung cancer cells exposed to ADC, and that these changes were partially mediated by the Akt-mTOR pathway." (PMID 30870998, 2019). "Targeting mTOR and AKT is a promising way to personalized treatment of lung cancer." (PMID 29788985, 2018). "Our results suggest that T4 has a more obvious effect on the viability of A549 and A549/DDP lung cancer cells when combined with the rapamycin, wortmannin and perifosine pretreatment; PI3K is upstream of AKT and mTOR; and mTOR is downstream of PI3K and AKT in the PI3K/AKT/mTOR signaling pathway." (PMID 28969040, 2017). "We examined different densities of A549 lung cancer cells and HSAEC2-KT normal lung cells side-by-side to see whether the EGFR-Akt-mTOR pathway is differentially regulated by cell type and cell density." (PMID 28061454, 2017). "Moreover, in a K-RAS mutant lung cancer mouse model, a combination of a MEK inhibitor at doses below the maximum tolerated dose with a PI3K/AKT/mTOR inhibitor was found to suppress the growth of the tumors." (PMID 28574827, 2017). "Not surprisingly, multiple components in the EGFR-Akt-mTOR pathway were highly expressed/activated in the A549 lung cancer cells but not in HSAEC-2KT normal lung cells, which is consistent with their oncogenetic functions." (PMID 28061454, 2017). "In case of lung cancer patients with chemoresistance and high expression of CD164, therapeutic targeting of mTOR might be considered as an alternative potential therapy." (PMID 28903328, 2017). "Previous preclinical studies showed that dual inhibition of PI3K/Akt/mTOR and MAPK/ERK pathways by combining two different small molecule kinase inhibitors led to more efficient growth inhibition than single pathway inhibition in both breast and lung cancers." (PMID 26565813, 2016). "Our findings have shown the potential of TATDN1 in regulating lung cancer metastasis, and that the Wnt/β-catenin signal pathways and PI3K/AKT/MTOR pathway may be involved in the key mechanism of its anti-metastatic effect." (PMID 26943769, 2016). "The results showed that with treatment of compound 5i, the PI3K/AKT/mTOR pathway was down-regulated in both H460 and A549 lung cancer cells in a dose-dependent manner, but not in H1975 lung cancer cells." (PMID 27786281, 2016). "Apart from measuring the IL-24 inhibitory effect on cell migration and invasion, we also investigated whether the AKT/mTOR signaling pathway that is downstream of SDF-1/CXCR4 axis and essential for lung cancer progression and metastasis was also affected." (PMID 25775124, 2015). "The finding of synergism in different cancer types with activating NRAS mutations is not surprising, because NRAS mutant melanoma, lung cancer and neuroblastoma all seem to depend on NRAS downstream signaling through MAPK and PI3K/AKT/mTOR." (PMID 25504439, 2015). "The purpose of this study was to examine whether 2 clinically approved mTOR inhibitors, temsirolimus and everolimus, overcome HGF-dependent resistance to EGFR-TKIs in EGFR mutant lung cancer cells." (PMID 23690929, 2013). "In order to test whether NBS1 indeed interacts with the mTOR/Rictor/SIN1 complex, co-immunoprecipitation assays using extracts from a lung cancer cell line H1299 were used." (PMID 23762398, 2013). "A review of patients with diabetes at the Cleveland Clinic found that those who had not been treated with metformin (see mTOR inhibitors section below) and/or thiazolidinediones were more likely to develop lung cancer." (PMID 24216701, 2013). "In the present study, we examined whether the clinically approved mTOR inhibitors, temsirolimus and everolimus, circumvent HGF-triggered EGFR-TKI resistance in EGFR mutant lung cancer cells using in vitro and in vivo models, and assessed underlying mechanisms." (PMID 23690929, 2013).
lung cancer (continued). "While a large number of mTOR inhibitors have been developed and are being evaluated in clinical trials in lung cancer, neither of sirolimus, temsirolimus, or everolimus, when used as monotherapeutic agents, show clinical efficacy in unselected NSCLC." (PMID 23690929, 2013). "Moreover, NVP-BKM120 when combined with the mTOR inhibitor RAD001 (Everolimus), managed to inhibit the growth of lung cancer cells in vitro and also in murine lung cancer xenograft models." (PMID 24281308, 2012). "In conclusion, our study establishes DCAF12 as a primary regulator of lung cancer metastasis through a dual mechanism: stabilizing the TRiC/CCT complex via non‐degradative ubiquitination to maintain cytoskeletal dynamics, and concurrently activating the YAP, STAT3, and mTOR pathways." (PMID 41047465, 2026). "Also in 2019, there were interesting data regarding lung cancer from a novel synthetic bromophenol derivative, BOS-93; this compound inhibited PI3K/Akt/mTOR and regulated the MAPK pathway to induce G0/G1 arrest, apoptosis, and autophagy in A549 lung cancer cells." (PMID 38894623, 2025). "In non‐small cell lung cancer, SSRIs limit tumor growth and increase tumor sensitivity to erlotinib by inhibiting the adenosine 5‐monophosphate adenosine 5‘‐monophosphate (AMP)‐activated protein kinase (AMPK)/mammalian target of rapamycin (mTOR) signaling pathway." (PMID 40937192, 2025). "For example, PKC-alpha and PKC-delta can phosphorylate and translocate MARCKS from the plasma membrane to the cytoplasm in smoke-related lung cancer, and the binding of MARCKS to calmodulin (CaM) could also result in the translocation of MARCKS to activate the downstream PI3K/AKT/mTOR pathway." (PMID 38755678, 2024). "However, following targeting of the 72 resistance genes we observed that only a very limited subset targeted for silencing were capable of preserving signalling through the PI3K, MAPK, and mTOR pathways, all known mediators of resistance in EGFR mutant lung cancer." (PMID 38658677, 2024). "Similarly, neither mTOR nor STAT3 alone served as a key determinant in lung cancer patient prognosis." (PMID 38886756, 2024). "The mammalian target of rapamycin (mTOR) pathway is a crucial pivot in cancer promotion and the mTOR-miR-143/HK2 axis could accelerate tumor proliferation and formation by promoting glucose metabolism in lung cancer." (PMID 37208722, 2023). "It was shown that A. vera and A. emodin are effective in lung cancer therapy by inhibiting cell proliferation, cytoskeleton activation, stimulated cell apoptosis as well as Cas‐3 and PKC activation, MAPK signalling, inhibition of ROS production, Akt/mTOR and PI3K/AKT pathways." (PMID 37697969, 2023). "In addition, Didemethoxylated curcumin may increase the sensitivity of cisplatin-resistant lung cancer cells to chemotherapy by inhibiting CA916798 (an over-expressed MDR protein) and PI3K/AKT/mTOR signaling, thus exerting antitumor activity and reversing MDR." (PMID 35684449, 2022). "In cases of lung cancer, KIF4A was reported to promote cell proliferation and migration and inhibit apoptosis in LUAD cell lines, whereas KIF18B was suggested to promote LUAD cell proliferation, migration, and invasion via the Rac1/Akt/mammalian target of rapamycin (mTOR) signaling pathway." (PMID 36499051, 2022). "Interestingly, S1P-induced IL-6, but not TNF-α, release from lung cancer-derived PBMCs was mTOR- and K-Ras-dependent, while NF-κB was not involved." (PMID 36010601, 2022).
lung cancer (continued). "Not only EGFR facilitates proliferative signaling through downstream signaling pathways, i.e. PI3K/AKT/mTOR and RAS/ERK, EGFR signaling pathway is one of the activated pathways in lung cancer and employs downstream RAS or ERK pathways to direct proliferative signaling for lung cancer cells." (PMID 34635059, 2021). "Accordingly, the ability of metformin to downregulate histone H3K4 methyltransferase in lung cancer cells could be independent of AMPK activation despite the contribution of the AMPK/mTOR signaling pathway to metformin-induced anticancer therapy." (PMID 33578894, 2021). "In both human and mouse lung cancer cell lines, knocking down HSP90AA1 promoted cell apoptosis through the inhibition of the pro-survival effect of AKT1 by decreasing the phosphorylation of itself and its downstream factors of mTOR and BAD, as well as downregulating Mcl1, Bcl-xl, and Survivin." (PMID 35095481, 2021). "Notably, DHA enhanced gefitinib-induced inhibition of NCI-H1975 lung cancer cells in migration and invasion via AKT/mammalian target of rapamycin (mTOR)/STAT3 signaling pathway, and co-administration of DHA and gefitinib induced cell cycle arrest in the G2/M phase 84." (PMID 33613116, 2021). "In lung cancer, a recent study demonstrated that the treatment of recipient cancer cells with EVs from gefitinib-resistant PC9 cells increased the phosphorylation of AKT and mTOR and enhanced proliferation, invasion, and drug resistance to gefitinib-induced apoptosis." (PMID 33671000, 2021). "In addition to onatasertib, other dual mTOR inhibitors, such as sapanisertib (NCT02417701) and vistusertib (NCT03106155), are also undergoing clinical trials in patients with stage IV or recurrent lung cancer." (PMID 34279440, 2021). "However, it has not been reported that baicalin can regulate the Akt/mTOR pathway and G1/S cell cycle pathway in lung cancer cells." (PMID 33585556, 2020). "Consistently, in NPM-ALK+ ALCL, as in EML4-ALK lung cancers and ALK-mutated neuroblastoma, a synergistic activity of ALK and mTOR inhibition had been described, although the authors did not investigate the involvement of autophagy associated with cell death in these settings." (PMID 33066037, 2020). "We also demonstrated that the lack of circHIPK3 might block tumorigenesis of lung cancer H1975 cells by damaging the activation of AKT/mTOR signaling pathway." (PMID 33817257, 2020). "Here, we exposed human lung cancer cells to extracts of a natural sea spray aerosol collected at the seashore in Belgium, a laboratory-generated SSA, the marine algal toxin homoyessotoxin and a chemical inhibitor of the mammalian target of rapamycin (mTOR) pathway." (PMID 30679557, 2019). "While the mTOR and MAPK cascade interactions are known to play a relevant role in lung cancer cell signal transductions, to our knowledge the interaction between p90RSK and BAD in the anti-apoptotic process has never been described and might represent a potential prognostic factor in lung cancer." (PMID 29137348, 2017). "The expression levels of PI3-K, PI3-P, AKT, TSC2, mTOR, p70S6K and 4E-BP1 were minimally affected by the wortmannin, perifosine, or rapamycin plus T4 treatments, but their phosphorylated products were greatly affected in A549 lung cancer cells and slightly affected in A549/DDP lung cancer cells." (PMID 28969040, 2017). "Moreover, compound 5i could induce G1 cell cycle arrest and autophagy in lung cancer cells through up-regulating P27, down-regulating CDK4 and cyclinD1 and attenuating PI3K/Akt/mTOR pathway." (PMID 27786281, 2016). "Therefore, 11βHSD2 inhibition represents a novel approach for lung cancer chemoprevention and therapy by increasing tumor glucocorticoid activity, which in turn selectively blocks local COX-2 activity and/or inhibits the ERK and mTOR signaling pathways." (PMID 26011146, 2015).